APOBEC1 (apolipoprotein B mRNA editing enzyme catalytic subunit 1)
Diseases named in the same sentence as APOBEC1 in open-access papers (continued):
Sharing a sentence is not in itself a finding about the gene and the disease.
pancreatic cancer (1 paper, 2024). "Apobec1 (apolipoprotein B mRNA editing enzyme, catalytic polypeptide 1) has been identified by bioinformatic analyses as a gene associated with pancreatitis and pancreatic cancer, although a specific role in AIP has not yet been established." (PMID 39595046, 2024).
skin cutaneous melanoma (1 paper, 2019). "An overwhelming excess of somatic mutations in APOBEC1 and APOBEC3A/B/G mutable motifs is likely to be due to the known excess of mutations in dipyrimidine dinucleotides (for example, TC) in skin cutaneous melanoma caused by mutagenic UV photoproducts." (PMID 30759888, 2019).
temporal lobe epilepsy (1 paper, 2017). A localization-related (focal) form of epilepsy characterized by recurrent seizures that arise from foci within the temporal lobe, most commonly from its mesial aspect. "Finally, we established a new PCR-based restriction fragment length polymorphism (RFLP) approach to profile mRNA expression with regard to the genetic APOBEC1 dimorphism of patients with intractable temporal lobe epilepsy (iTLE) and found that the patients fall into two groups." (PMID 29375302, 2017).
cancer (26 papers, 2012 to 2025). A tumor composed of atypical neoplastic, often pleomorphic cells that invade other tissues. "APOBEC1 was initially characterized as playing a role in cholesterol maintenance and lipid metabolism and is associated with cancer." (PMID 41272765, 2025). "Although the sources of mutations driving oncogenesis can be many, the aim of the study was to explore the contribution of APOBEC1 cytidine deaminase to the large number of point mutations and rearrangements evidenced in many cancer genomes." (PMID 31726973, 2019). "Interestingly, APOBEC1 expression and editing is enhanced in several human cancers, but this association appears to be more related to the ability of APOBEC1 to deaminate DNA rather than RNA." (PMID 37510291, 2023). "In addition, overexpression of APOBEC1 leads to the editing of additional cytidine sites in the substrate, which is considered to be the main cause of abnormal mutation in cancer cells." (PMID 36339709, 2022). "A potential role in disease for APOBEC1 has been envisioned since its discovery: Overexpression of APOBEC1 in the liver of several animal models induces cancer and its deficiency in cancer-prone mice reduces the onset of neoplastic lesions." (PMID 33376192, 2021). "However, in a recent study of 32 tumor types from the TCGA, the authors found a striking correlation of APOBEC1 upregulation in tumors bearing a high number of in-frame indel mutations in various cancer cohorts including PDAC." (PMID 32545414, 2020). "Moreover, a fine analysis of mutational footprints was able to extract a specific APOBEC1 mutational motif that can be found in many human cancer genomes." (PMID 31726973, 2019). "It is possible, therefore, that these changes, associated with APOBEC1 mutagenic activity, may also be boosting its oncogenic potential and drive both the onset and the progression of cancer." (PMID 25085003, 2014). "Before kataegis was described, genome sequencing studies had revealed that many cancers have somatic mutations dominated by C-to-T transitions and that overexpression of APOBEC1 was associated with cancer development when overexpression of APOBEC3A induced genomic damage and mutations." (PMID 24966870, 2014). "Both PLEKHG5 and APOBEC1 were previously suggested as valuable prognostic biomarkers and potential anti‐tumor targets for different cancers." (PMID 40045917, 2025). "Mutational signatures that are characterized by cytosine mutations in TC dinucleotides, which are reflective of APOBEC1 and relevant APOBEC3 activities in cancer genomes, have been detected in over 50% of cancers and most cancer types." (PMID 38254863, 2024). "APOBEC1 has rarely been considered as a contributor to SBS2/SBS13 mutation burden in cancer or normal tissues because of its small intestine-specific expression profile." (PMID 36702998, 2023). "Based on the data from the TCGA database and GTEx database, we analyzed the transcription levels of APOBEC1/3A/APOBEC3G/3H in many kinds of cancer tissues, adjacent tissues and normal tissues." (PMID 36339709, 2022). "APOBEC1 can deaminate single-stranded DNA or RNA, and its deamination activity is related to cancer." (PMID 36339709, 2022). "Inhibition by APOBEC3 proteins has been addressed in the context of HIV infection and cancer, suggesting that inhibition of APOBEC1 is feasible." (PMID 32545414, 2020). "That the APOBEC3A, APOBEC3B, and APOBEC3G footprints are more abundant in comparison with the APOBEC1 and AID motifs suggests an important role for these three deaminases in generating somatic C:G>A:T mutations in human cancers." (PMID 30759888, 2019). "These physiological functions of APOBEC1 help explain mechanisms by which overexpression of APOBEC1 can initiate cancer." (PMID 28572915, 2017). "Using Tag-seq, 53 transcripts that had greater SBS in cancer were present among APOBEC1 RNA-editing targets, and 8 of them had been experimentally validated." (PMID 23137041, 2012).
cancer (continued). "We crossed this APOBEC1 list of RNA-editing targets with the 372 transcripts (=301 NCBI gene ID after synergizer conversion) that showed greater SBS frequencies in cancer than in healthy cells using L-SAGE experiments." (PMID 23137041, 2012). "The transversions associated with APOBEC1, APOBEC3A, and APOBEC3B were found to be more abundant in comparison with APOBEC3G and AID, suggesting a role of these three deaminases in generating C:G>G:C somatic mutations in human cancer." (PMID 30759888, 2019). "APOBEC1 has been linked to cancer development in mice but its oncogenic mechanisms are not yet well understood." (PMID 25085003, 2014). "Together with previous findings linking APOBEC1 presence/absence with the induction of tumors in mice, our experimental results and our observations in EACs indicate that APOBEC1 could be involved in the onset of cancer by targeting genomic DNA directly." (PMID 25085003, 2014). "And that might because APOBEC1 behave as a consistently hypo-methylated gene in pan-cancer." (PMID 33083119, 2020). "Although the genomic sequences of the tumor and the healthy cells were not simultaneously available in our study, these SBS could not be attributed to known SNP, catalogued cancer related somatic mutations, and known APOBEC1 or ADAR editing." (PMID 23137041, 2012). "When comparing with COSMIC database, Signature B was similar to Signature 2, which has been identified in variety cancer types, and possibly affected by the activity of APOBEC family of cytidine deaminases, especially APOBEC1/3A/3B." (PMID 32489320, 2020). "The beta-2 microglobulin was the only transcript common to both APOBEC1 RNA-editing targets and transcripts with greater SBS in healthy than cancer cells." (PMID 23137041, 2012). "Of note, APOBEC1 and APOBEC3A expression were only detected in a handful of cancers, such as APOBEC1 in PAAD, in contrast to APOBEC3G, which was detected in most cancer types." (PMID 36969056, 2023). "In summary, our research reveals that APOBEC1/3A/3G/3H plays a carcinogenic role in the occurrence and development of PAAD and is expected to become a new biomarker and therapeutic target for this type of malignant tumor." (PMID 36339709, 2022). "APOBEC1-mediated RNA editing has been studied for one cancer, and cancers have not been surveyed for the prevalence of APOBEC3-mediated C-to-U RNA editing." (PMID 31717692, 2019). "Finally, for transcripts with greater SBS in healthy than cancer obtained using Tag-seq, only 1, namely FARSB, had a 17 base NlaIII tag that overlapped the APOBEC-1 RNA-editing site." (PMID 23137041, 2012). "In addition to this direct APOBEC1/3A−SDH interaction, RNA editors can also manipulate non-coding RNA levels in cancers and non-cancer diseases." (PMID 33153035, 2020).
tumor (12 papers, 2012 to 2025). "While Apobec3 mutational activity has been demonstrated in mice, Apobec1 emerged as tumor plasma cell-specific potential promoter of SBS2 and SBS13." (PMID 38714690, 2024). "Similarly, the APOBEC1 controls testicular germ cell tumor susceptibility and embryonic viability through transgenerational epigenetic inheritance." (PMID 35692843, 2022). "Therefore, the immunosuppressive effect of APOBEC1 in the PAAD tumor microenvironment and the genomic instability caused by the high expression of APOBEC3A/3G/3H in PAAD tissues may be important factors in the occurrence and development of PAAD." (PMID 36339709, 2022). "First, we used the data from the PAAD project in the TISIDB database to explore the relationship between APOBEC1/3A/3G/3H expression and the level of tumor infiltrating cells and multiple immunomodulators based on various immunological markers in PAAD." (PMID 36339709, 2022). "In summary, these results further indicate that APOBEC1/3A/3G/3H play important roles in the immune regulation of the tumor microenvironment in PAAD." (PMID 36339709, 2022). "First, APOBEC1 was negatively correlated with the infiltration level of many kinds of immunoreactive tumor-infiltrating cells, including Tem_CD4, Tem_CD8 and NK cells, and negatively correlated with the expression level of most immune promoters." (PMID 36339709, 2022). "Future experimental studies can further confirm the tumor-promoting role of APOBEC1/3A/3G/3H in PAAD." (PMID 36339709, 2022). "In this study, we found that APOBEC1 was also highly expressed in PAAD tissues and was significantly associated with higher PAAD tumor grade and shorter OS and RFS." (PMID 36339709, 2022). "In contrast, Apobec1 expression was mostly restricted to the tumor plasma cells." (PMID 38714690, 2024). "In addition, the coexpression of APOBEC1/3A/3G/3H and a variety of tumor-promoting genes and their activation of a variety of tumor-promoting pathways may be a potential mechanism for promoting the occurrence and development of PAAD." (PMID 36339709, 2022). "The “RAS/MAPK signaling pathway” and “RTK signaling pathway” can promote the growth and proliferation of tumor cells, while the “TSC/mTOR signaling pathway” can promote tumor angiogenesis, which may be another mechanism by which APOBEC1 plays a carcinogenic role." (PMID 36339709, 2022). "In addition, the role of APOBEC1/3A/3G/3H in the immune regulation is diverse and complex, the high expression of APOBEC1 may inhibit the infiltration level of many kinds of immunoreactive tumor-infiltrating cells, which may be an important factor leading to immune escape of PAAD cells." (PMID 36339709, 2022). "Indeed the expression levels of APOBEC1, APOBEC3B, APOBEC3C and APOBEC3F were found to be significantly higher in both primary and metastatic tumours as compared with normal tissues (P<0.01)." (PMID 26647728, 2015). "Our results show that the roles of APOBEC1/3A/3G/3H in tumor immune regulation are not consistent." (PMID 36339709, 2022). "In addition, APOBEC1/3A/3G/3H may promote the occurrence and development of PAAD by activating a variety of carcinogenic pathways and regulating PAAD tumor immunity." (PMID 36339709, 2022). "Interestingly, increased expression of APOBEC1 and editing of NF1 were also found in CRC, suggesting that other tumor types could also be affected by this pathway." (PMID 30619092, 2018).
infection (3 papers, 2018 to 2025). The state of being infected such as from the introduction of a foreign agent such as serum, vaccine, antigenic substance or organism. "Three of these experimental models (ST cells, piglet jejunums and 2D organoids) were shown to overexpress apolipoprotein B mRNA editing catalytic polypeptide-like 1 (APOBEC1) during infection." (PMID 41272765, 2025). "No significant change was observed with the expression of ADAR1–3, APOBEC1, APOBEC2, and APOBEC3A 3D, 3G, and 3H, whereas APOBEC3B, and 3C had a significant decrease, and APOBEC3F had a significant increase in A549 cells during the course of infection with H7N9." (PMID 29363430, 2018).
metabolic disease (1 paper, 2018). A congenital disorder (due to inherited enzyme abnormality) or acquired (due to failure of a metabolically important organ) disorder resulting from an abnormal metabolic process. "Despite efforts made to identify other RNA editing targets of APOBEC1, no other target has yet been shown to play a role connecting APOBEC1-mediated RNA editing with metabolic disease." (PMID 30619092, 2018).
APOBEC1 also shares sentences with these, for which no sentence is quoted: steatosis (2 papers); adrenocortical carcinoma (1); Aicardi–Goutières Syndrome (1); AIDS (1); Barrett esophagus (1); bladder cancer (1); cardiovascular diseases (1); diffuse large B-cell lymphoma (1); dyslipidemia (1); endometrial carcinoma (1); endometrial tumors (1); gastrointestinal tumors (1); Gliosis (1); gout (1); head and neck squamous cell carcinoma (1); Hypercholesterolemia (1); kidney injury (1); lung carcinoma (1); lung squamous cell carcinoma (1); lymphoid neoplasm (1); mesothelioma (1); neurological diseases (1); pancreatitis (1); pneumococcal pneumonia (1); pneumocystis pneumonia (1); pneumonia (1); stomach adenocarcinoma (1).